NUP214 (nucleoporin 214)
Diseases named in the same sentence as NUP214 in open-access papers (continued):
Sharing a sentence is not in itself a finding about the gene and the disease.
acute myeloid leukemia (32 papers, 2006 to 2025). Acute myeloid leukemia (AML) is a group of neoplasms arising from precursor cells committed to the myeloid cell-line differentiation. "Several uncommon translocations associated with acute myeloid leukemia (AML) involve the NUP214 gene, and the corresponding fusion proteins are involved in leukemic transformation." (PMID 41002427, 2025). "Chromosomal translocations involving the nucleoporin NUP214 have been described in de novo and therapy-related acute myeloid leukemia (AML) as well as acute lymphoblastic leukemia (ALL)." (PMID 32934780, 2020). "DEK was discovered to be an oncogene as a fusion with NUP214 gene, which results in producing DEK-NUP214 proteins, in a subset of patients with acute myeloid leukemia." (PMID 32656741, 2020). "NUP214 forms a fusion gene with the DEK gene on chromosome 6 in a t translocation associated with acute myeloid leukemia and myelodysplastic syndrome." (PMID 31221207, 2019). "DEK was originally identified as a fusion protein with the CAN/NUP214 nucleoporin in a patient with acute myeloid leukemia harboring the chromosomal translocation (t6;9)(p23;q34)." (PMID 29538372, 2018). "DEK was originally identified in acute myeloid leukemia as a fusion protein with NUP214, and was subsequently shown to be overexpressed at the mRNA and protein levels in various cancer types including squamous cell carcinoma (SCC)." (PMID 28558019, 2017). "This suggests that treatment options for NUP98 rearranged acute myeloid leukemia may be adaptable to NUP214 rearranged acute myeloid leukemia patients but further evidence is needed." (PMID 37901324, 2023). "The nuclear export protein XPO1 interacts with nucleoporin 214 (NUP214) and has been implicated in the pathogenesis of SET::NUP214 acute myeloid leukemia (AML)." (PMID 40148556, 2025). "The oncogene DEK is located on human chromosome 6p22.3 and was originally identified as a fusion to the 3′ portion of the chromosome 9 NUP214 (CAN) gene in a specific subtype of acute myeloid leukemia (AML) patients." (PMID 35563178, 2022). "It was originally identified as a fusion with CAN/NUP214 nucleoporin in a subset of acute myeloid leukemia (AML) patients, and was named on the basis of the initials of the patient DK." (PMID 23902796, 2013). "Nup98-fusions are found most frequently in acute myeloid leukemia (AML), while Nup214-fusions are detected in T-cell acute lymphoblastic leukemia (T-ALL) as well as in AML." (PMID 31755865, 2019).
acute lymphoblastic leukemia (15 papers, 2009 to 2025). Leukemia with an acute onset, characterized by the presence of lymphoblasts in the bone marrow and the peripheral blood. "SET-CAN/NUP214 fusion is a recurrent event most commonly seen in T-cell acute lymphoblastic leukemia (T-ALL)." (PMID 33869055, 2021). "In the 2022 international consensus classification of acute lymphoblastic leukemia/lymphoma, SET-CAN/NUP214 fusion gene positive has been listed as a subtype of the HOXA gene family in the latest eight temporary entities." (PMID 37909026, 2023). "Another fusion protein involving NUP214 is NUP214-SET, which is created from a different chromosomal translocation and was identified in patients with T-acute lymphoblastic leukemia (T-ALL), implicating disparate leukemogenic driver mechanisms." (PMID 39080077, 2024). "Furthermore, despite no direct links have been so far established between NUP214 and autophagy, a fusion involving NUP214 and the sequestosome-1 (SQSTM1) protein, which is required for proper autophagy induction, has been connected with acute lymphoblastic leukemia." (PMID 37535687, 2023). "NUP214::ABL1 fusion is detected in 6% of T-cell acute lymphoblastic leukemia (T-ALL), and is very rare in B-ALL." (PMID 36172171, 2022).
acute leukemia (13 papers, 2014 to 2025). A clonal (malignant) hematopoietic disorder with an acute onset, affecting the bone marrow and the peripheral blood. "We examined 9 cases of acute leukemia with NUP214 rearrangement by array Comparative Genomic Hybridization (aCGH), reverse-transcription polymerase chain reaction (RT-PCR), and cycle sequencing/Sanger sequencing to detect which fusion genes had been generated." (PMID 38571499, 2024). "Flow cytometry data indicated that the markers CD34, CD33, CD13, and CD7 were common in SET-CAN/NUP214 positive acute leukemia, including ALL." (PMID 35905214, 2022). "Chromosomal translocations involving the NUP214 locus are recurrent in acute leukemia and frequently fuse the C-terminal region of NUP214 with SET and DEK, two chromatin remodeling proteins with roles in transcription regulation." (PMID 30669574, 2019). "Alterations of the NUP214 gene (9q34) are recurrent in acute leukemias." (PMID 38571499, 2024). "Regarding NUP214, although there have been few studies on its relationship with thyroid tumors, chromosomal translocations involving the NUP214 locus were found to be recurrent in acute leukemia." (PMID 35923625, 2022). "Chromosomal translocations involving the NUP214 locus are a recurrent event in acute leukemia." (PMID 30669574, 2019). "Bleximenib, for instance, is currently being tested in a pediatric cohort (12 years and older) of the phase 1/2 study (cAMeLot-1) for acute leukemia patients harboring KMT2A, NPM1, NUP98, or NUP214 alterations (NCT04811560)." (PMID 41154380, 2025). "Chromosomal translocations fusing the locus of nucleoporin NUP214 each with the proto-oncogenes SET and DEK are recurrent in, largely intractable, acute leukemias." (PMID 32934780, 2020).
breast carcinoma (7 papers, 2016 to 2025). "XPO1 and NUP214, two associated proteins whose regulatory targets are mutually upregulated in high-ColX module tumors, have collectively been described as drivers of breast cancer and markers of poor survival in pancreatic cancer." (PMID 39939916, 2025). "Other members of the nucleoporin family have been linked with cancer including Tpr, NUP62, NUP214 and NUP358/RanBP2 with NUP88 and more recently, NUP43 specifically linked to poor outcome in breast cancer." (PMID 30935371, 2019). "Taken together, we found 13 previously known high-risk gene fusions of breast cancer such as BCAS3-BCAS4, NOTCH- NUP214, MED13- BCAS3 and CARM-SMARCA4, and 8 potential drivers such as SULF2-ZNF217, MED1-ACSF2." (PMID 27506935, 2016).
HIV-1 infection (4 papers, 2012 to 2023). The type species of lentivirus and the etiologic agent of acquired immunodeficiency syndrome (AIDS). "Knockdown of Nup214, an FG-Nup that also is thought to regulate the flow of cargo, also had a greater positive effect on WT HIV-1 infection." (PMID 37355754, 2023). "By contrast, depletion of Nup62 or Nup214 elevated WT HIV-1 infection, and Nup54 and Nup58 knockdown enhanced infection of both WT and CA mutant HIV-1." (PMID 37355754, 2023). "NUP358, NUP214, NUP98 and NUPL2 have been described as cytoplasmic filament nucleoporins and have all been previously implicated in HIV-1 infection." (PMID 30496303, 2018). "Investigation of the mechanistic role in HIV-1 infection of Nup214/CAN, which was found in another screen, revealed that it only plays an indirect role through its effect on mRNA export." (PMID 23049930, 2012). "Effects of NUP88 and NUP214 depletion on HIV-1 infection and MX2 activity were generally similar." (PMID 30084827, 2018). "Notably, knock-down of NUP214, NUP62 or NUP98 had minimal effects (<2-fold) on HIV-1 infection in control cells, indicating that each of these nucleoporins promote MX2 anti-viral function." (PMID 30496303, 2018). "Our results are in good general agreement with their findings that depletion of NUP214 or TNPO1 impair MX2 anti-viral function in HeLa cells, and also with the apparently variable nucleoporin requirements for HIV-1 infection and MX2 activity among different cell lines." (PMID 30496303, 2018). "Moreover, some Nup depletions (SEH1, NUP85, NUP160, SEC13, NUP98, NUP107, ELYS/ACHTF1, NUP93, NUP205, NUP88, and NUP214) that reduced both HIV-1 infection and MX2 activity in dividing HeLa cells, affected MX2 activity but not HIV-1 infection in non-dividing HeLa cells." (PMID 30084827, 2018).
myeloid leukemia (4 papers, 2013 to 2020). A clonal proliferation of myeloid cells and their precursors in the bone marrow, peripheral blood, and spleen. "Later, recurrent translocations involving SET and CAN (also called Nup214), a nucleoporin, were found to be associated with several distinct malignancies, including myeloid leukemias, colorectal, oral, and ovarian cancers." (PMID 26339295, 2015). "Our laboratory previously established the association and reciprocal regulation of Rac1 and SET/I2PP2A (inhibitor 2 of protein phosphatase 2A), a nuclear proto-oncogene which, as a protein-fusion with Nup214, is associated with myeloid leukemia." (PMID 23874639, 2013).
acute promyelocytic leukemia (3 papers, 2017 to 2023). An aggressive form of acute myeloid leukemia (AML), characterized by arrest of leukocyte differentiation at the promyelocyte stage, due to a specific chromosomal translocation t(15;17) in myeloid cells. "Importantly, PCR assays have been developed for three AML phenotypes: (i) acute promyelocytic leukemia (APL) (fusion gene PML::RARA); (ii) patients with NPM1 and CBF–AML (RUNX1::RUNX1T1 and CBFB::MYH11); and (iii) AML with fusion genes BCR::ABL1, KMT2::MLLT3, and DEK::NUP214." (PMID 37345204, 2023).
myeloid neoplasm (3 papers, 2017 to 2026). Proliferation of myeloid cells originating from a primitive stem cell. "Selective XPO1 inhibitors (selinexor, eltanexor) show preferential activity in NPM1-mutated, DEK::NUP214-positive and SF3B1-mutated myeloid neoplasms." (PMID 42071259, 2026).
neuroblastoma (3 papers, 2010 to 2023). Neuroblastoma (NB) is the most common solid, extracranial childhood tumor. "The S12 neuroblastoma cell line was chosen for this analysis as it displays each of the three permutations of NUP62/NUP214 immunolabeled NPC types." (PMID 22558357, 2012).
ovarian carcinoma (3 papers, 2012 to 2021). A malignant neoplasm originating from the surface ovarian epithelium. "Western blot analyses revealed that knockdown of NUP62 or NUP214 to ∼25% of control levels resulted from treatment of TOV112D cells (derived from a high grade ovarian carcinoma) with combinations of targeted siRNAs." (PMID 22558357, 2012). "Ovarian carcinoma TOV112D cells and COS7 cells displayed two major populations of NPCs: peripheral rim NUP62+/NUP214− and contralateral surface NUP62−/NUP214+ NPCs, with few NUP62+/NUP214+ NPCs observed." (PMID 22558357, 2012).
brain injury (2 papers, 2021 to 2023). Acute and chronic (see also brain INJURIES, CHRONIC) injuries to the brain, including the cerebral hemispheres, CEREBELLUM, and brain STEM. "(F, G) Adult Drosophila expressing Nup62 RNAi or Nup214 RNAi in neuronal cells exposed to repeated traumatic brain injury (TBI) were raised on RU486 (+ RU486) or ethanol (-RU486) treated food for 20 days before motor assays." (PMID 34060470, 2021).
virus infection (2 papers, 2020 to 2022). "Immediately prior to virus infection, the levels of NUP214 mRNA and Nup214 protein in knockdown cells were determined with RT-PCR and Western blotting, respectively." (PMID 32256144, 2020). "Knockdown of Rae1, mTor, Nup88 or Nup214 did not restore VP2 expression under mutant CrPV(R146A) virus infection compared to wild-type infection, similar to that observed in the control dsRNA treated cells." (PMID 36455064, 2022).
amyotrophic lateral sclerosis (1 paper, 2022). Amyotrophic lateral sclerosis (ALS) is a neurodegenerative disease characterized by progressive muscular paralysis reflecting degeneration of motor neurons in the primary motor cortex, corticospinal tracts, brainstem and spinal cord. "Moreover, several potential disease-causing genes were detected and markedly enriched in the pathways of neurodegeneration (including WNT16, RYR3 and RYR1 genes) and amyotrophic lateral sclerosis (ALS, including NUP205, CAPN2, and NUP214 genes)." (PMID 35355568, 2022).
arthrogryposis (1 paper, 2024). A rare, non-progressive congenital disorder characterized by multiple joint contractures which are present at birth. "Further research is required to elucidate the mechanism of production of arthrogryposis by NUP214 gene variants." (PMID 39650934, 2024). "We described a fetus with hydrops and arthrogryposis with homozygous recessive consensus splice site variant c.46-2A>G in the NUP214 gene." (PMID 39650934, 2024).
B-cell neoplasm (1 paper, 2025). A group of heterogeneous lymphoid tumors generally expressing one or more B-cell antigens or representing malignant transformations of B-lymphocytes. "Whole-exome sequencing revealed an elevated somatic copy number alteration burden and pathogenic variants in ARID1A, KMT2D, BCL7A, PTPN11, and NUP214, suggesting disruptions in chromatin remodeling, B-cell neoplasm pathogenesis, and oncogenic signaling driving the tumorigenesis." (PMID 41378284, 2025).
cardiovirus infection (1 paper, 2022). "Most importantly, FG-NUPs that had previously been shown to be hyperphosphorylated during cardiovirus infection: NUP62, NUP98, NUP153 and NUP214 exhibited statistical significance." (PMID 36508477, 2022).
cyst (1 paper, 2019). A sac-like closed membranous structure that may be empty or contain fluid or amorphous material. "Depletion of Nup62, Nup214 or Nup88 in cyst cells led to cell-autonomous defects in mRNA export in Drosophila." (PMID 31492028, 2019).
Epstein-Barr virus infection (1 paper, 2017). An infection that is caused by Epstein-Barr virus. "Additionally, the pathway ‘Epstein-Barr virus infection’ was simultaneously enriched, in which several genes including BCL2, CD39, HSP70, HDAC45, IL10, IL10R and vimentin were up-regulated, together with some down-regulated genes such as CD38, NUP214, RBP-Jκ, CycA, TAK1 and TBK1." (PMID 28912500, 2017).
glioma (1 paper, 2024). A benign or malignant brain and spinal cord tumor that arises from glial cells (astrocytes, oligodendrocytes, ependymal cells). "miR-1208 targets METTL3’s 3′UTR region, diminishing NUP214 levels, and inhibiting glioma cell proliferation." (PMID 38474421, 2024). "Additionally, IGF2BP2 stabilizes transcripts like NUP214 and FLOT1, influencing glioma progression and TMZ resistance." (PMID 38474421, 2024).
head and neck squamous cell carcinoma (1 paper, 2023). A squamous cell carcinoma that arises from any of the following anatomic sites: lip and oral cavity, nasal cavity, paranasal sinuses, pharynx, larynx, and salivary glands. "Repression of NUP214 by ectopic expression of miR-133b, a miRNA down-regulated in head and neck squamous cell carcinoma, delays mitotic progression in HCT116 cells." (PMID 37535687, 2023).
hydrops (1 paper, 2024). "Herein, we describe for the first time, a fetus with hydrops and arthrogryposis multiplex with a homozygous novel consensus splice site variant in the NUP214 gene, chr9:g.131127522A>G or c.46-2A>G (transcript ID NM_005085.4)." (PMID 39650934, 2024). "This case report is the first description of a fetus with hydrops and arthrogryposis multiplex with a homozygous novel consensus splice site variant in the NUP214 gene." (PMID 39650934, 2024).
influenza (1 paper, 2020). An acute viral infection of the respiratory tract, occurring in isolated cases, in epidemics, or in pandemics; it is caused by serologically different strains of viruses (influenzaviruses) designated A, B, and C, has a 3-day incubation period, and usually lasts for 3 to 10 days. "In conclusion, here we have shown that the influenza A virus NS2 protein interacts with the amino-terminal FG domain of the Nup214 protein in yeast and human-originated cells, and influenza viral replication is suppressed in the knockdown cells for this protein." (PMID 32256144, 2020). "This study showed that there is a relationship between human Nup214 and NS2 protein, which is known to play a role in the nucleo-cytoplasmic transport of influenza vRNPs." (PMID 32256144, 2020).
lymphoid leukemia (1 paper, 2024). A malignant lymphocytic neoplasm of B-cell or T-cell lineage involving primarily the bone marrow and the peripheral blood. "NUP98–and to a lesser extent, NUP214–have been found to be part of various fusion events involved in the development of several different myeloid and lymphoid leukemias." (PMID 38562379, 2024).
metastatic prostate carcinoma (1 paper, 2025). A carcinoma that arises from the prostate gland and has spread to other anatomic sites. "In addition, elevated levels of other NUPs downregulated by bromoxib in TPP (i.e., NUP188, NUP210, NUP85, NUP62, and NUP214) were identified in metastatic prostate cancer, suggesting that NPC dysregulation may drive aggressive cancer phenotypes." (PMID 40137294, 2025).
myeloma (1 paper, 2025). "Our mutation profile (ARID1A, KMT2D, BCL7A, PTPN11, NUP214) and high CNV load converge with patterns reported across extramedullary/myeloma cohorts, notably MAPK pathway lesions and 1q amplifications." (PMID 41378284, 2025).
ovarian tumor (1 paper, 2012). "In contrast, NUP214 siRNA treatment of TOV112D cells for extended periods (longer than one week) resulted in death of TOV112D ovarian tumor cells, followed by colonial growth of some remaining cells." (PMID 22558357, 2012).
plasma cell neoplasm (1 paper, 2025). A clonal proliferation of immunoglobulin-secreting plasma cells. "These somatic alterations have been implicated in various processes central to plasma cell neoplasms, from chromatin remodeling (ARID1A, KMT2D, and BCL7A) to oncogenic signaling (PTPN11, NUP214)." (PMID 41378284, 2025).
T-cell leukemia (1 paper, 2022). A malignant disease of the T-lymphocytes in the bone marrow, thymus, and/or blood. "Elevated NUP214 expression correlated with the presence of fusion gene SET-NUP214 in MEGAL, which reportedly activates HOXA genes in T-cell leukemia." (PMID 35328612, 2022).